BDNF (brain derived neurotrophic factor)
Diseases named in the same sentence as BDNF in open-access papers (continued):
Sharing a sentence is not in itself a finding about the gene and the disease.
Alzheimer disease (continued). "Moreover, transplantation of as-miR-937-expressing MSCs significantly reduced the deposition of Abeta, increased the levels of BDNF, and significantly improved the appearance of mice in an Alzheimer’s Disease model." (PMID 27354158, 2016). "In Alzheimer’s disease, chronic inflammation in the brain exacerbates the pathological condition and cognitive decline because inflammation is toxic to neurons and suppresses the production of neurotrophic factors such as BDNF, GDNF and NGF." (PMID 25760987, 2015). "In Alzheimer’s disease (AD), the expression of BDNF is reduced." (PMID 25601223, 2015). "Recently we studied the miRNA expression pattern in a human Alzheimer's disease (AD) brain sample and Tg2576 AD transgenic mouse brain, and found that the level of miR-206, which regulates brain derived neurotrophic factor (BDNF), was markedly increased in AD mice." (PMID 24959881, 2014). "There is accumulating evidence that neurotrophins, like brain-derived neurotrophic factor (BDNF), may impact aging and Alzheimer’s Disease." (PMID 24086677, 2013). "In the mature brain, however, upregulation of miR-103 may suppress BDNF synthesis in humans and promote neuropathological processes in a mouse model of Alzheimer’s disease." (PMID 23451123, 2013). "Moreover, TrkB.T1 is up-regulated in neurodegenerative disorders such as Alzheimer's disease suggesting that imbalances in expression between the TrkB.FL and truncated TrkB isoforms makes BDNF signaling ineffective and contributes to neuronal damage." (PMID 22761934, 2012). "BDNF has recently garnered significant attention as a potential therapeutic target for neurodegenerative diseases such as Alzheimer disease (AD), but emerging evidence suggests that BDNF may also be mechanistically involved in the pathogenesis of AD." (PMID 22870188, 2012). "Accordingly, an increased level of p35 might be caused by an increase of protein stabilization by BDNF and/or by an up-regulation following a down-regulation of miR-107, leading to hyperactivation of CDK5 in Alzheimer's disease." (PMID 21625387, 2011). "It has been suggested that the early memory dysfunction seen in Alzheimer’s disease may be related to the levels of BDNF in the hippocampus." (PMID 22654716, 2011). "Another study conducted on individuals with Alzheimer disease demonstrated that aerobic training combined with resveratrol and fisetin supplementation markedly boosted hippocampal expression of neurogenesis‐related genes, BDNF, VEGF, and FGF7 in mice injected with amyloid‐beta." (PMID 40735395, 2025). "In Alzheimer’s disease mouse models, primary cultures of mouse NSCs engineered to overexpress BDNF showed improved survival, neuronal differentiation, synaptic maturation, and cognitive performance; these effects were reversed by BDNF knockdown, confirming its mechanistic relevance." (PMID 40806396, 2025). "DA has also been suggested to stimulate brain-derived neurotrophic factor (BDNF) production, which promotes neuron growth and survival, playing a crucial role in maintaining neuronal health and potentially slowing the progression of neurodegenerative diseases like Alzheimer's disease (AD)." (PMID 41189497, 2025). "Additionally, this approach may benefit other neurodegenerative conditions or neuropsychiatric disorders involving altered BDNF levels, such as Huntington’s disease, Alzheimer’s disease, and schizophrenia." (PMID 39200225, 2024). "BDNF is known to facilitate neurogenesis, neuroprotection, and neuroregeneration, and reduced BDNF concentration is observed in patients with CAD, and may constitute a pathogenic factor common to Alzheimer’s disease." (PMID 38961824, 2024). "Another of NTs is brain-derived neurotrophic factor (BDNF), which, due to its potential neuroprotective effects, is the subject of much research in developing therapies for diseases such as Parkinson’s disease, amyotrophic lateral sclerosis, Alzheimer’s disease, and glaucoma." (PMID 38562304, 2024).
Alzheimer disease (continued). "BDNF may be an indirect target of Notch1 in a research of Alzheimer’s disease." (PMID 39090706, 2024). "BDNF and its receptor TrkB are extensively expressed in neurons of the central nervous system (CNS), and the contribution of the BDNF/TrkB system to neuronal function is evident; thus, its downregulation has been considered to be involved in the pathogenesis of Alzheimer’s disease (AD)." (PMID 38338875, 2024). "As the minuscule quantities of endogenous BDNF in the brain have hampered the delineation of its physiopathology as well as a clear understanding of its cell biology, quantitative aspects are also discussed, including post-mortem measurements of BDNF levels in Alzheimer’s disease." (PMID 37470055, 2023). "However, BDNF/TrkB variants have not been identified thus far as risk factors associated with Alzheimer’s disease in human genetic studies." (PMID 37470055, 2023). "Estrogen receptors colocalize to some neuronal populations that express BDNF and TrkB to regulate BDNF/TrkB expression and distribution, and this relationship has been shown to play a role in neurodegenerative diseases such as Parkinson’s and Alzheimer’s disease." (PMID 35338053, 2022). "Indeed, it has been reported that a decreased level of BDNF may contribute to the degeneration of specific neuronal populations and progressive atrophy of neurons in the Alzheimer's disease-affected brain." (PMID 35964077, 2022). "Furthermore, BDNF could attenuate cognitive decline in Alzheimer’s disease models and the dopaminergic neurodegeneration in PD models." (PMID 35804280, 2022). "Therefore, β-glucans increasing BDNF in the PFC may contribute to the enhancement of cognition and preventing neurodegeneration and reducing the risk of Alzheimer's disease." (PMID 35308288, 2022). "Furthermore, these findings indicate that BDNF may be a promising avenue in the development of drug therapies in the prevention or treatment Alzheimer’s disease." (PMID 34017238, 2021). "Given that decreased histone acetylation and BDNF levels are associated with aging-related cognitive decline and that patients with Alzheimer’s disease have reduced BDNF expression, LIPUS may also be beneficial to cognitive function in aging and Alzheimer’s disease." (PMID 30341248, 2019). "Thus, maintaining the production of BDNF in neuronal cells may be an important strategy for the prevention or treatment of neurodegenerative diseases, such as Alzheimer’s disease." (PMID 31861353, 2019). "Therefore, the regulation of BDNF formation may be a key point for the treatment or prevention of neurodegenerative diseases such as Alzheimer’s disease." (PMID 31861353, 2019). "Therefore, BDNF is a favorable candidate for Alzheimer’s disease (AD) genetic studies." (PMID 29867348, 2018). "Importantly, BDNF is known to protect against tau-related neurodegeneration in Alzheimer's disease." (PMID 29551980, 2018). "In conclusion, a gene therapy construct has been designed that aims to provide long-term signaling via the BDNF-TrkB pathway and neuroprotection against a variety of pathophysiological insults that are encountered in neurological diseases ranging from glaucoma to Alzheimer's disease." (PMID 29466871, 2018). "Growing evidence that changes in cerebral BDNF levels and in the BDNF-TrkB signaling pathway may be involved in the etiopathogenesis of Alzheimer’s disease (AD) has suggested that blood BDNF could be used as a biomarker for AD diagnosis, prognosis, and treatment monitoring." (PMID 29330839, 2018). "Previous studies reported the use of small molecule BDNF mimetics that inhibit Aβ-induced neuritic dystrophy and neuronal death in hippocampal slice cultures, demonstrating the relevant potential role of molecular mimetics in the therapeutics of Alzheimer’s disease." (PMID 23320097, 2013).
Alzheimer disease (continued). "In summary, there is a marked reduction in BDNF levels in both the cortex and ChBF in Alzheimer’s disease, and this may have a bearing on support for cholinergic neurons as well as a deficit in LTP with wide significance for synaptic plasticity in a number of different neurons." (PMID 22654716, 2011). "In addition, since SSRI antidepressants are known to elevate BDNF levels, research and clinical trials are being carried out to investigate the effect of these in Alzheimer’s disease; one such antidepressant, Citalopram, is currently undergoing Phase II clinical trials." (PMID 22654716, 2011). "Brain-derived neurotrophic factor (BDNF) can protect neurons from apoptosis and maintain normal synaptic structures, indicating a significant potential for Alzheimer's disease (AD) treatment." (PMID 41480410, 2026). "In rodent models of Alzheimer’s disease (e.g., APP/PS1 and 5xFAD), butyrate administration has been shown to reverse Aβ-induced cognitive impairment by restoring hippocampal BDNF expression and activating downstream CREB/TrkB signaling pathways." (PMID 41299728, 2025). "An Alzheimer’s disease (AD) study also demonstrated that FXR overexpression interacts with CREB, decreasing CREB and BDNF protein levels, increasing amyloid-β (Aβ) deposition, and aggravating Aβ-induced neuronal apoptosis." (PMID 40362260, 2025). "In experimental models of Alzheimer’s disease (AD), induced by streptozotocin (STZ), the levels of TrkB receptor and BDNF mRNA expression in the hippocampus are drastically reduced." (PMID 41169479, 2025). "A fluorescence-based detection platform was developed for brain-derived neurotrophic factor (BDNF), a key biomarker of Alzheimer’s disease (AD)." (PMID 39942807, 2025). "HIIT ameliorates cerebral neurodegeneration by upregulating hippocampal PINK1, Parkin, and BDNF proteins, promoting AMP-dependent protein kinase expression, and reducing amyloid-β protein accumulation in Alzheimer’s disease models." (PMID 40035032, 2025). "Roflumilast, in an Alzheimer’s disease (AD) model using APP/PS1 double transgenic mice, showed reduced neuronal death, increased cAMP/CREB/BDNF signaling, and improved Bcl-2/Bax ratios." (PMID 39851514, 2025). "Here, it has also been drawn to neuro-degenerative disorders like Alzheimer’s disease (AD), Parkinson’s disease (PD), and amyotrophic lateral sclerosis (ALS)—where decreased BDNF leads to synaptic dysfunction and cell death." (PMID 40362507, 2025). "Recently, the brain-derived neurotrophic factor (BDNF) and circulating arginine metabolites were suggested as potential biomarkers of Alzheimer’s disease (AD)." (PMID 38339164, 2024). "Other investigators have also reported that plant-derived compounds improve memory functions in animal models of Alzheimer’s disease via increasing CREB and BDNF." (PMID 37456525, 2023). "In an Alzheimer’s disease rodent model, Diminazene, an ACE2 activator was found to increase CREB, BDNF, and nicotinic receptors while reducing apoptotic and inflammatory proteins which all play a major role in adult neurogenesis." (PMID 36353605, 2022). "The hippocampus also expresses and relies heavily on proteins such as brain-derived neurotrophic factor (BDNF), which is known to be decreased in Alzheimer’s disease." (PMID 36611911, 2022). "Decreased BDNF and impaired TRKB signaling contribute to neurodegeneration in Alzheimer’s disease (AD)." (PMID 36170028, 2022). "High-frequency rTMS can considerably upregulate brain-derived neurotrophic factor (BDNF) levels, which decline within the hippocampus in patients with Alzheimer disease." (PMID 33416500, 2021). "Previous studies of our group demonstrated that PBMT ameliorated dendritic atrophy via upregulation of BDNF and reduced Aβ levels by activating the PKA/SIRT1 signaling pathway in an Alzheimer's disease model." (PMID 33859781, 2021).
Alzheimer disease (continued). "The expression levels of neurotrophic factors, such as brain-derived neurotrophic factor (BDNF), glial cell line-derived neurotrophic factor, and vascular endothelial growth factor, can be increased by LIFU in the rat models of Alzheimer’s disease." (PMID 35145384, 2021). "Consumption of OF has also been shown to alter the expression of brain-derived neurotrophic factor (BDNF) and N-methyl-D-aspartate (NMDA) receptor subunits in the rodent brain and improve cognitive function in a rodent model of Alzheimer’s disease." (PMID 32709093, 2020). "This study shows that serotonergic neurons alter neural stem cell proliferation and neurogenesis via a complex neuron-glia interaction involving interleukin-4, BDNF and NGF receptor in a zebrafish model of Alzheimer's disease." (PMID 31905199, 2020). "Recently, Schipke and colleagues proposed the combined measurement of six different blood markers, BDNF, IGF-1, VEGF, TGF-beta 1, MCP-1 and IL-18 to identify Alzheimer’s disease patients." (PMID 32098256, 2020). "A recent study conducted using the FAD5X mice model for Alzheimer’s disease also found that ASA binds to peroxisome proliferator-activated receptor alpha (PPARα) and upregulates the expression of brain-derived neurotrophic factor (BDNF) in hippocampal neurons." (PMID 31671812, 2019). "Here, we show that total sulfated GAGs from hippocampus of Alzheimer’s disease have altered capacities to bind and potentiate the activities of growth factors including FGF-2, VEGF, and BDNF while their capacity to bind to tau is remarkable increased." (PMID 30608949, 2019). "Studies have shown that the levels of brain derived neurotrophic factor (BDNF) and its tropomyosin kinase B (TrkB) receptor are decreased in the hippocampus and the cerebral cortex at the beginning of the Alzheimer’s disease." (PMID 30477087, 2018). "Several studies have identified significant contrasting differences in BDNF levels between healthy and MCI/dementia/Alzheimer's disease (AD) participants." (PMID 29109736, 2017). "An interesting study aimed at correlating PPARα activation and the expression of brain-derived neurotrophic factor (BDNF) in hippocampal neurons demonstrated an improved learning and memory in an animal model of Alzheimer disease via PPARα." (PMID 27013951, 2016). "Accumulating evidence shows that brain-derived neurotrophic factor (BDNF) and its receptor tropomyosin-related kinase B (TrkB) significantly decrease early in Alzheimer's disease (AD)." (PMID 25942043, 2015). "Low levels of BDNF have been found inconsistently in the ASD literature but more consistently in the aging and Alzheimer Disease literature." (PMID 25225482, 2014). "An altered expression of brain-derived neurotrophic factor (BDNF, N-terminal half of which is predicted to be disordered) was found in postmortem brains and serum from patients with schizophrenia, Alzheimer's disease and mood disorders." (PMID 25988147, 2014). "In clinical trials, GDNF has been used in the treatment of Parkinson's disease, BDNF in the treatment of ALS, and NGF as a therapeutic agent in Alzheimer's disease." (PMID 24391835, 2013). "Two neurotrophic factor candidates for such a pivotal role in the progression of Alzheimer’s disease are NGF and BDNF." (PMID 22654716, 2011). "This aim of this study was to investigate the effects of a 12-week multimodal exercise program on cognitive function, motor performance, and plasma levels of brain-derived neurotrophic factor (BDNF) and cytokines in elderly individuals with Alzheimer’s disease (AD)." (PMID 40869831, 2025). "The decline in neurotrophic factor levels, particularly brain-derived neurotrophic factor (BDNF) and its receptors, is a well-documented physiological event in neurodegenerative conditions like Alzheimer’s disease, Parkinson’s disease, multiple sclerosis and amyotrophic lateral sclerosis." (PMID 39935805, 2024).
Alzheimer disease (continued). "In this regard, an emerging line supports the role of BDNF/TrkB signaling pathway as a compensatory response that delays symptoms in the early stage of Alzheimer’s disease, while in later stages, they would not be sufficient to prevent neurodegeneration." (PMID 36674698, 2023). "In the current study, the amyloid-β protein was not assessed, and the relation between BDNF, amyloid-β protein, and Alzheimer’s disease must be cautiously discussed." (PMID 39484298, 2023). "There was no concordance between the hippocampal and blood BDNF levels that agreed with previous reports of post mortem studies on subjects with Alzheimer’s disease, those with mood disorders, and healthy controls." (PMID 38203674, 2023). "A recent study reported that irisin could induce brain-derived neurotrophic factor (BDNF) expression in rat hippocampus and play a key role in the beneficial effects of exercise on synaptic plasticity and memory in Alzheimer’s disease models." (PMID 35627690, 2022). "Both BDNF and GDNF are known for its neuroprotective effects in different pathologies of central and peripheral nervous systems, including hypoxic and ischemic damage, traumas, neurodegenerative diseases, Parkinson disease, and Alzheimer disease." (PMID 36077134, 2022). "On the other hand, pretreatment with BDNF prevented MAPK phosphorylation activated by amyloid-beta peptide in the entorhinal cortex of Alzheimer’s disease, suggesting a negative correlation of BDNF with MAPK signaling." (PMID 33631722, 2021). "Furthermore, afamelanotide stimulates BDNF expression in the brain by activating MC4R to mediate neurogenesis and cognitive function in an Alzheimer’s disease animal model." (PMID 34836030, 2021). "Our chemical induction method significantly upregulated various trophic factors, such as BDNF, GDNF, NGF, and NT-3, which have been reported to have therapeutic effects in neurodegenerative diseases, such as Alzheimer’s disease, Parkinson’s disease, and Amyotrophic lateral sclerosis." (PMID 33104750, 2020). "Mounting evidence that alterations in brain-derived neurotrophic factor (BDNF) levels and signaling may be involved in the etiopathogenesis of Alzheimer’s disease (AD) has suggested that its blood levels could be used as a biomarker of the disease." (PMID 29330839, 2018). "Generally, decreased BDNF levels in MCI may contribute to the development of neurodegenerative diseases such as dementia and Alzheimer's disease." (PMID 29109736, 2017). "A neuroprotective effect of BDNF against Alzheimer’s disease has also been demonstrated in rodents and non-human primates." (PMID 21255124, 2011). "In addition to playing an important role in Alzheimer’s disease and memory impairment in patients with traumatic brain injury (TBI), brain-derived neurotrophic factor (BDNF) and nerve growth factor (NGF) are extremely important for the rehabilitation of patients with stroke." (PMID 40109842, 2025). "In a study of Alzheimer's disease, it was suggested that overexpression of NMDAR could lead to increased intracellular Ca2+ levels, which would then lead to the excessive activation of calpain, thus affecting the activity and expression of BDNF." (PMID 38615365, 2024). "Studies comparing cerebrospinal fluid and serum BDNF measurements in a sample of patients with Alzheimer’s disease found that they do not correlate and that BDNF concentrations in serum or plasma are much higher than in cerebrospinal fluid, possibly due to peripheral synthesis." (PMID 38137853, 2023). "Recent data suggest that irisin is expressed in the brain and induces brain-derived neurotrophic factor (BDNF) expression in rat hippocampus, thus increasing brain irisin levels could preserves memory and hinders cognitive destruction in an Alzheimer’s disease rat model study." (PMID 35195223, 2022).